ADIRF (adipogenesis regulatory factor)
Description:
Plays a role in fat cell development; promotes adipogenic differentiation and stimulates transcription initiation of master adipogenesis factors like PPARG and CEBPA at early stages of preadipocyte differentiation. Its overexpression confers resistance to the anticancer chemotherapeutic drug cisplatin.
Synonyms: apM-2; AFRO; APM2; C10orf116
Tractability: PROTAC: ubiquitination databases record sites on it.
Gene: Protein-coding gene on chromosome 10 (86,968,432 to 87,007,922, forward strand). Ensembl gene ENSG00000148671.
Subcellular location: Nucleus
Subcellular location (Human Protein Atlas): Cytosol; Nucleoplasm
Pathways (Reactome):
Developmental Biology: Transcriptional regulation of white adipocyte differentiation
Gene Ontology:
Molecular function: protein binding
Biological process: positive regulation of fat cell differentiation; positive regulation of transcription by RNA polymerase II
Cellular component: extracellular exosome; nucleoplasm; nucleus
Genetic constraint (gnomAD): Loss-of-function variants: 10 observed, 8.86 expected, observed/expected ratio (o/e) 1.13, 90% interval 0.69 to 1.79. That is too few expected variants to judge how well the gene tolerates losing a copy. Missense variants: 106 observed, 87.03 expected, observed/expected ratio (o/e) 1.22, 90% interval 1.04 to 1.43. Synonymous variants: 48 observed, 36.64 expected, observed/expected ratio (o/e) 1.31, 90% interval 1.04 to 1.66.
Homologues: Orthologues: chimpanzee ADIRF (100% identical), pig ADIRF (91% identical), dog ADIRF (82% identical), macaque ADIRF (75% identical).
Diseases named in the same sentence as ADIRF in open-access papers:
ADIRF is named in the same sentence as 17 diseases in open-access papers, as found by Europe PMC text mining. Sharing a sentence is not in itself a finding about the gene and the disease. The quoted sentences say what the papers report.
gastric cancer (3 papers, 2013 to 2022). A primary or metastatic malignant neoplasm involving the stomach. "Adipogenesis regulatory factor (ADIRF,), also known as C10orf116 or APM2, was underexpressed in gastric cancer and manifested a significant relationship with higher pathological stage, higher clinical stage, lymph node metastasis, and poorer distant relapse-free survival." (PMID 35030964, 2022).
Obesity (2 papers, 2016 to 2023). Accumulation of substantial excess body fat. "Higher expression of this gene in obese individuals, suggesting a role for ADIRF in the development of obesity." (PMID 37252399, 2023). "Interestingly, ADIRF is also highly expressed in obese individuals, suggesting a role for this gene in the development of obesity." (PMID 27685785, 2016).
ovarian carcinoma (2 papers, 2013 to 2021). A malignant neoplasm originating from the surface ovarian epithelium. "Our results show that ADIRF, SLC2A5, C3orf86, HSPA1B are among the most significant PCa biomarkers, while MTRNR2L1, EEPD1, TEPP and VN1R2 are jointly important biomarkers across prostate, breast and ovarian cancers." (PMID 34001952, 2021).
prostate carcinoma (2 papers, 2015 to 2024). A carcinoma that arises from epithelial cells of the prostate gland. "For instance, ADIRF protein in urine exosomes can serve as a biomarker for prostate cancer." (PMID 39765560, 2024). "Other promising prostate cancer biomarkers are LAMTOR1 and ADIRF (81% sensitivity at 100% specificity)." (PMID 26196085, 2015).
urothelial carcinoma (1 paper, 2015). A malignant neoplasm derived from the transitional epithelium of the urinary tract (urinary bladder, ureter, urethra, or renal pelvis). "ADIRF was also the top ranking transcriptional regulator in the TCGA SCCL-down gene lists, supporting a role in urothelial carcinoma." (PMID 26008846, 2015).
tumor (7 papers, 2013 to 2025). "ADIRF, tumor-associated genes CLU, FAM13C, as well as NGF, PRELP, RERG, PTGIS, GPC3 genes were among the top 20 overexpressed genes in EcE stromal cell population." (PMID 39169201, 2024). "Cluster 0 contributed to lymphocyte regulation, cluster 1 was cCAFs (classical CAFs), involving in extracellular matrix related components and cluster 2 was tumor associated PSCs (pancreatic stellate cells), expressing marker genes such as RGS5 and ADIRF." (PMID 35733218, 2022). "Our results showed that the relative mRNA expression of ADIRF, MT2A, MT1M, and JUNB was downregulated after TGF-beta treatment and/or tumor stimulation, while the expression level of C11orf96 was upregulated, even after tumor stimulation." (PMID 33777046, 2021).
cancer (3 papers, 2013 to 2022). A tumor composed of atypical neoplastic, often pleomorphic cells that invade other tissues. "Adipogenesis regulatory factor (ADIRF), ranked among the top candidates, correlates with resistance to cisplatin in several cancer cell types." (PMID 26196085, 2015).
cardiovascular diseases (1 paper, 2022). "In the dilated stage, TMEM205, ADIRF, C6H4orf48, NGRN, PROSER1, ERICH2, and CINP were not previously linked to cardiovascular diseases." (PMID 35625658, 2022).
ADIRF also shares sentences with these, for which no sentence is quoted: breast carcinoma (1 paper); breast tumor (1); cystadenoma (1); gynecological cancers (1); hepatocellular carcinoma (1); liver fibrosis (1); lymph node metastasis (1); mucinous adenocarcinoma (1); prostate tumour (1).